LEP (leptin)
Diseases named in the same sentence as LEP in open-access papers (continued):
Sharing a sentence is not in itself a finding about the gene and the disease.
Obesity (continued). "Importantly, previous studies indicate autophagy malfunction in hypothalamic POMC neurons contributes to obesity-associated metabolic dysfunctions, including increased plasma insulin levels, hyperglycemia, glucose intolerance, impaired lipolysis, and leptin resistance." (PMID 30972025, 2019). "To exam whether leptin mediates the effect of polygenic risk on obesity from childhood to young adulthood, we tested for mediation effect of baseline leptin on GPSleptin–BMI associations adjusting for baseline age, sex, residence, pubertal stages, and other lifestyle factors." (PMID 31285522, 2019). "Therefore, we examined whether the proportions VIS APs would be affected by both dietary and genetic (leptin-deficient ob/ob) obesity." (PMID 31597091, 2019). "Therefore, the association of obesity and the increased leptin levels with the response to treatment should be also investigated in breast cancer patients to better understand the response to immunotherapy as well as the better control of the appearance of side effects." (PMID 31380268, 2019). "Obesity and therefore leptin are implicated as central triggers of unnecessary or aggressive inflammatory state responsible for autoimmune states and the increased incidence of autoimmunity could be a function of increased leptin, while in men testosterone acts as an immunosuppressant." (PMID 31110493, 2019). "Thus, adipose tissue-linked systemic inflammation in KO vs. WT mice might be indicated by higher levels of leptin and resistin, adipokines contributing to the systemic low-grade inflammatory milieu in obesity and associated metabolic disorders." (PMID 31349725, 2019). "Altogether, these data illustrate that reduced leptin regulation of thermogenesis may be a mechanism that explains how a preexisting reduction in leptin sensitivity in the DMH predisposes rats to exacerbated obesity." (PMID 31342663, 2019). "Further studies are needed to elucidate whether specific milk-derived miRNAs, such as those differentially expressed in overweight/obese in comparison with normal-weight mothers, could be involved in the mechanisms underlying a loss of leptin functionality in the case of obesity." (PMID 31661820, 2019). "Similarly, differences in circulating leptin and insulin concentrations have been linked to acyclicity in oestrous cycles of horses as a result of obesity, which may be linked to gut microbiome structure." (PMID 30770764, 2019). "Additionally, chronobiological melatonin aspects and their interrelationship with cytokines produced by adipocytes such as leptin and adiponectin have been evaluated and promising results in the prevention and control of complications caused by obesity have been suggested." (PMID 31489938, 2019). "We aimed to investigate a possible sleep-gene interaction for childhood obesity risk, and whether the interaction in childhood longitudinally contributes to obesity risk at a 10-year follow-up and further to test if there is any mediation through the leptin pathway." (PMID 31285522, 2019). "A multitude of factors and conditions can affect E2 metabolism (inflammation, hypoxia/oxidative stress, obesity/insulin resistance/leptin, diet, drugs, and genetic polymorphisms of metabolizing enzymes), suggesting that PAH heterogeneity may be due, at least in part, to dysregulated E2 metabolism." (PMID 31877978, 2019). "Notably, other loci such as MC4R, PCSK1, and BDNF, are well known to be associated with severe early-onset obesity and harbor genes involved in the regulation of leptin-melanocortin pathways in the hypothalamus, thus are thought to affect body weight largely through impacting appetite." (PMID 31285522, 2019). "Additionally, selenoprotein M (SelM) was found to support hypothalamic leptin signaling, which may underlie the obesity phenotype observed in SelM KO mice." (PMID 31340540, 2019).
Obesity (continued). "However, several rodent studies have shown that suckling pups of mothers who were fed high-fat diets to induce obesity were programmed to develop insulin and leptin resistance and subsequent metabolic disorder, predisposing the offspring to develop obesity later in life." (PMID 31141526, 2019). "However, while leptin has been associated with hypertension, vascular diseases, and inflammation in the context of obesity, it remains unknown whether its daily administration could further impair cardiovascular function in patients with lipodystrophy." (PMID 31656583, 2019). "This could be interpreted as an association between a biomarker that well defines the age-related transition to menopause and whose increasing levels are linked to weight gain (FSH) with a biomarker that has been widely related to obesity and metabolic risk (leptin)." (PMID 31509577, 2019). "Therefore, epigenetic regulation of LEP may represent the mechanism underlying the protective effect of breastfeeding duration against obesity." (PMID 31464656, 2019). "Leptin is implicated in obesity-associated CRC, but the underlying mechanism remains unclear." (PMID 31506433, 2019). "Interestingly, insulin resistance is associated with a sharp decrease in Treg cells in several animal models of obesity such as leptin-deficient mice (Leprob/ob), mice heterozygous for the yellow spontaneous mutation, and male mice chronically fed a high-fat diet (HFD)." (PMID 31297120, 2019). "Thus, obesity is associated with hyperleptinemia and leptin resistance." (PMID 29971101, 2018). "Interestingly, clinically relevant concentrations of trypsin- and pepsin-digested wheat gluten was demonstrated to hinder the binding between leptin and its receptor, indicating that gluten could be linked to leptin resistance and obesity." (PMID 30428550, 2018). "However, given the pleiotropic action of leptin, a systematic approach to modulate their levels and thus prevent obesity-associated disorders might be, for the moment, unavailable." (PMID 29910742, 2018). "The precise mechanisms linking rapid eye movement (REM) sleep and obesity are incompletely understood, but may include decreased sleeping metabolic rate, and endocrine changes associated with decreased leptin and increased ghrelin levels promoting increased food consumption." (PMID 30042730, 2018). "Finally, exposure to hypoxia has been shown to stimulatehypoxia inducible factor 1, which appears to be an important regulator for theexpression of the leptin gene – a hormone secreted by adipose tissue thatproduces negative feedback on appetite – and inversely associated with obesity." (PMID 28853330, 2018). "Sleeping less than 7 h may cause reciprocal changes in circulating levels of leptin and ghrelin which would increase appetite, caloric intake, reduce energy expenditure facilitating an increase in waist circumference as well as overall obesity development." (PMID 29895272, 2018). "Indeed, extreme phenotyping is a refinement of this practice and has had some notable successes in identifying genes implicated in quantitative traits, including obesity and obstructive sleep apnoea, for which obesity and leptin levels are significant risk factors." (PMID 30121879, 2018). "Therefore, dysregulated adiponectin and leptin signaling may mediate the detrimental impact of obesity on CNS and raise the risk for cognitive decline and AD." (PMID 30692905, 2018). "Therefore, central leptin resistance, caused by impairment of leptin transportation, leptin signaling and leptin target neural circuits, is considered the main risk factor for the obesity pathogenesis.." (PMID 29910742, 2018). "Interestingly, amylin appears to have a synergistic effect with leptin: pre-treatment with amylin reduces the leptin resistance observed in obesity and leads to a mean weight loss of 12.7% when given in combination with recombinant leptin in a proof of concept trial." (PMID 30158899, 2018).
Obesity (continued). "The presence of increased ghrelin levels in CR-Leptin rats in adulthood, which are known to be protected from the increased susceptibility to develop obesity characteristic of maternal calorie restriction, could seem controversial when considering the orexigenic actions of ghrelin." (PMID 29618984, 2018). "Specifically, this analysis tested the hypothesis of whether bifidobacteria and lactobacilli were 1) linked to T2D and opioid use, and 2) linked to circulating leptin and oxytocin representing obesity-T2D and pro-social psychological hormone markers, respectively." (PMID 29596446, 2018). "In view of the worldwide increase in obesity among pregnant women and the contribution of maternal obesity to offspring obesity, the aim of this study was to investigate the association between maternal plasma concentrations of leptin and adiponectin and newborn adiposity." (PMID 28241462, 2017). "Our findings show that this polymorphism is also associated with insulin resistance independently of obesity in girls, suggesting that it might have a potential effect or flag a functional polymorphism that has an effect on the action of leptin on insulin metabolism." (PMID 28771179, 2017). "Genetic factors (such as genetic predisposition) and hormonal factors (such as leptin resistance), microbiological factors (including intestinal flora) and certain illnesses (such as those caused by Adenoviruses) can encourage the development of obesity in childhood." (PMID 37152086, 2017). "In addition, hypothalamic inflammation associated with diet-induced obesity could contribute to leptin resistance by altering the cellular networks and molecular pathways that control energy homeostasis." (PMID 28377744, 2017). "Because leptin action in brain reduces food intake and body weight by regulating DA signaling, adaptive changes in DA synaptic markers may be causally related to the pathogenesis of obesity in humans." (PMID 28824395, 2017). "Importantly, leptin-deficiency-associated obesity successfully resolves upon treatment with recombinant leptin, clearly indicating the major physiological role of leptin in the regulation of whole-body energy homeostasis." (PMID 28592656, 2017). "A previous study suggested that HSC senescence in high fat diet-fed mice is driven by obesity-related changes in the intestinal microbiome, and the intestinal microbiome is abnormal in leptin-deficient ob/ob mice and obese humans, many of whom are suspected to be leptin-resistant." (PMID 28427343, 2017). "Leptin affects BP in an apparently opposite way: on the one hand it causes chronic increase in BP and may contribute to obesity related hypertension, while on the other hand its metabolic actions (lowering appetite and increasing energy expenditure) tend to reduce BP." (PMID 28270795, 2017). "The present findings justify further research to determine if these cells also lose Smo activity when deprived of leptin, as this might provide a unifying mechanism to explain the complex phenotype the develops in the context of monogenic leptin-deficient obesity." (PMID 28427343, 2017). "Furthermore, we provide evidence that levels of local and systemic survivin are regulated in obesity, and we identify a close relationship between survivin and leptin, an adipokine associated with a damaging inflammatory and antiapoptotic environment that favors tumor growth and cancer progression." (PMID 28518147, 2017). "As it is known that leptin levels are markedly increased in obese subjects this could be another possible mechanism for the impaired NK cell function and increased cancer risk observed during obesity." (PMID 28690853, 2017). "To test whether therapeutic silencing of Fsp27 might be useful to improve obesity, fatty liver, and glycemic control, we used antisense oligonucleotides (ASOs) in both nutritional (high-fat diet) and genetic (leptin-deficient ob/ob) mouse models of obesity, hyperglycemia, and hepatosteatosis." (PMID 27884961, 2017).
Obesity (continued). "Obesity is associated with pro-inflammatory responses, which may be mediated in part by leptin." (PMID 29358937, 2017). "Leptin deficiency leads to obesity and concomitant hormonal changes that might exert a neurotrophic effect on brainstem circuits, e.g., increased levels of amylin and insulin, that may perhaps compensate over time for the lack of leptin’s neurotrophic action in ob/ob while the animals gain weight." (PMID 29250032, 2017). "Finally, obesity is associated with leptin and decreased adiponectin." (PMID 28819564, 2017). "Thus, restoration of leptin signaling could result in better functional outcomes in neurodegenerative disease states, especially those associated with obesity and metabolic disorders." (PMID 28154473, 2017). "Furthermore, current data indicate that obesity induces higher NILCO expression in EmCa that might be linked to leptin signaling." (PMID 28659656, 2017). "Here, we summarize current knowledge suggesting the mesolimbic dopamine system regulates physical activity, obesity-induced impairments in dopamine signaling may cause physical inactivity, and central leptin resistance in obesity and T2D may alter physical activity in a dopamine-dependent manner." (PMID 28588553, 2017). "Therefore, the excessive intake of saturated fatty acids may cause ER stress and leptin resistance in obesity." (PMID 27375555, 2016). "The elevated leptin level could be a response to obesity which is a risk factor for stroke." (PMID 27739518, 2016). "A landmark discovery in the field of obesity genetics was the identification of mutations in the leptin gene in grossly obese children followed by identification of mutations in other genes involved in energy regulation pathways laying down the basis for monogenic obesity." (PMID 27075752, 2016). "We also showed for the first time that PPARGC1α DNA methylation levels in placenta likely contribute to mediate the relationship between maternal glycemia and cord blood leptin levels, which could explain why these newborns have an increased risk of obesity and T2D later in life." (PMID 27340502, 2016). "Recently it was demonstrated that leptin may influence hyperuricemia associated with obesity." (PMID 26640613, 2016). "Furthermore, certain adipokines, such as leptin, are mainly associated with total obesity, whereas others, such as IL-6 and adiponectin may be more closely linked with abdominal obesity." (PMID 27567677, 2016). "Moreover, FADD‐D mutation was associated with prevention of genetic obesity, such as obesity resulting from leptin deficiency, due to enhanced energy expenditure caused by PPAR‐α‐mediated upregulation of genes participating in fatty acid oxidation in adipose tissues." (PMID 27357657, 2016). "In addition, obesity could cause leptin resistance and increase activity of the renin-angiotensin-aldosterone system, which ultimately cause increased peripheral vascular resistance and elevated blood pressure." (PMID 27663794, 2016). "Our findings suggest that miR-4443 acts in a tumor-suppressive manner by down-regulating TRAF4 and NCOA1 downstream of MEK-C/EBP-mediated leptin and insulin signaling, and that insulin and/or leptin resistance (e.g. in obesity) may suppress this pathway and increase the risk of metastatic CRC." (PMID 27842582, 2016). "Also, leptin levels increase with obesity and diabetes, diseases associated with bone fragility." (PMID 27708616, 2016). "Indeed, human obesity is also associated with a degree of hypothalamic leptin resistance, which may contribute to HPO dysregulation in PCOS." (PMID 27375552, 2016). "Interestingly, the substitution of saturated by unsaturated fatty acids in the diet has beneficial effects on modulation of hypothalamic inflammation and function in obesity, underlying, at hypotalamic level, the interaction among insulin and/or leptin resistance, AMPK activation and hyperphagia." (PMID 27375435, 2016).
Obesity (continued). "However, the experimental studies in rodents reporting an increase in the incidence of haemorrhagic transformation have used different models of obesity including the leptin-deficient ob/ob mouse and high-fat-fed rats or a different model of cerebral ischaemia." (PMID 26239227, 2015). "Although only leptin is secreted by the adipocyte cell, both, insulin and leptin, are the predominant adiposity signals in circulation, and therefore were chosen to assess the effects of obesity associated endocrine signals in prostate cancer cell proliferation." (PMID 25928422, 2015). "Furthermore, extensive studies have revealed an increase in Hsp70 synthesis due to obesity stress that may incite oxidative stress and also plays a critical role in leptin resistance that is connected to the risk of reproductive diseases." (PMID 26305539, 2015). "Hence, leptin potentially contributes to many cardiovascular risks associated with obesity." (PMID 26557089, 2015). "In addition to the close association between leptin levels and obesity, the results of the present study suggested that leptin may partly account for the effect of obesity on IDD." (PMID 25892402, 2015). "Intrahippocampal administration of IL-1 receptor antagonist was protective against obesity-induced neurophysiological dysfunction, indicating that leptin deficiency, via promotion of a pro-inflammatory environment in the brain, may therefore contribute directly to cognitive decline." (PMID 25802557, 2015). "In addition to serve as an adipose signal for the long-term regulation of food intake, energy expenditure and body weight, leptin may contribute to the metabolic and vascular risk associated with obesity." (PMID 26030149, 2015). "Indeed, brain permeable NtsR-1-specific agonists decrease feeding and body weight in normal mice, as well as in leptin-deficient obese mice, suggesting that Nts action via NtsR-1 may be useful in treating obesity." (PMID 25741247, 2015). "Because the adiposity hormone leptin participates in the regulation of both energy homeostasis and thermoregulation, leptin-deficient ob/ob mice are characterized not only by severe obesity, but by hypothermia when housed at temperatures below thermoneutrality." (PMID 25756181, 2015). "However, despite an abundance of epidemiological data linking obesity and cancer and a large body of in vitro observations confirming a relationship between leptin and obesity-related tumorigenesis, the mechanisms underlying this cross-talk remains unclear." (PMID 25857300, 2015). "We hypothesized that the JNK/STAT3-signaling pathway which is one of the main mechanisms activated by leptin and associated with excess proliferation and inhibition of apoptosis plays a role in the obesity-related mitochondrial dysfunction observed in colon cancer." (PMID 26472027, 2015). "Based on these observations, it is reasonable to suggest that pharmacological approaches targeting leptin's effects could represent a potentially useful therapeutic strategy for the treatment of obesity-associated hypertension among other cardiovascular disease." (PMID 26379553, 2015). "Furthermore longitudinal studies in young Japanese adults reveal elevations in plasma noradrenaline levels precede both weight gain and increases in plasma leptin levels suggesting hyperleptinemia is ancillary to sympathetic stimulation associated with obesity." (PMID 26064978, 2015). "Finally, I will explore how hypothalamic SIRT1 may be involved in age-associated weight gain and diet-induced obesity by regulating leptin and insulin sensitivity in the central nervous system." (PMID 26236282, 2015). "Also in this context, there are proposed influences of adipokines, such as leptin and adiponectin, and also insulin, on central mechanisms of energy balance, causing irreversible changes in hypothalamic neural interconnections leading to obesity and cancer." (PMID 25874125, 2015).